XBP1 (X-box binding protein 1)
Diseases named in the same sentence as XBP1 in open-access papers (continued):
Sharing a sentence is not in itself a finding about the gene and the disease.
Cerebral ischemia (4 papers, 2019 to 2024). Restriction of arterial blood supply to the brain associated with insufficient oxygenation to support the metabolic requirements of the tissue. "This study demonstrated that downregulated XBP-1 could inhibit pyroptosis by inhibiting the NLRP3/Caspase-1/GSDMD pathway in the hippocampus which rescues cerebral ischemia/reperfusion injury." (PMID 35497095, 2022). "Several molecular events indicating induction of ER stress after global brain ischemia were documented, e.g. post-ischemic phosphorylation of eIF2α, expression of CHOP and ATF4 or splicing of XBP1." (PMID 37452223, 2023). "However, clear evidence that the increased expression and slicing of XBP-1 induced pyroptosis is present in cerebral ischemia/reperfusion has not yet been demonstrated." (PMID 35497095, 2022).
cervical carcinoma (4 papers, 2011 to 2024). A carcinoma arising from either the exocervical squamous epithelium or the endocervical glandular epithelium. "Park and Ozcan pointed out that ERS regulated the survival or apoptosis of tumor cells through IRE1α–XBP1, PERK–eIF2α, and ATF6 pathways, and ERS was activated in the occurrence and development of cervical cancer." (PMID 36406049, 2022). "In HeLa cervical cancer cell line, γ-T3 and δ-T3 induces ER stress via the activation of IRE1 pathway, which in turn mediates the alternative splicing of X-box binding protein 1 (XBP-1) mRNA and modulates CHOP transcription, leading to subsequent activation of caspase-9, -8, and -12." (PMID 30654580, 2019). "In order to determine if the inhibition of Tm-induced XBP1 mRNA splicing by RTA was also observed in transformed cells, the experiments were repeated in HeLa cells, a human cervical carcinoma cell line, which is also responsive to RTA as shown in our previous work." (PMID 22069719, 2011).
diabetic cardiomyopathy (4 papers, 2018 to 2024). Diabetic cardiomyopathy is a disorder of the heart muscle in people with diabetes. "However, phosphorylation of XBP1 at S348 and SUMOylation of XBP1 at K276 promote its nuclear translocation, ameliorating the progression of diabetic cardiomyopathy." (PMID 39355507, 2024). "Studies have shown that linagliptin may be able to protect patients with diabetic cardiomyopathy from IRE1α-XBP-1 pathway-mediated ER stress." (PMID 29721506, 2018). "Empagliflozin has also been found to induce a protective effect against diabetic cardiomyopathy by inhibiting IRE1a-Xbp1 and ATF4-CHOP pathways, whilst it can also improve β-cell mass in streptozotocin-treated mice through down-regulation of Xbp1, BiP and ATF4." (PMID 33467546, 2021).
influenza (4 papers, 2020 to 2024). An acute viral infection of the respiratory tract, occurring in isolated cases, in epidemics, or in pandemics; it is caused by serologically different strains of viruses (influenzaviruses) designated A, B, and C, has a 3-day incubation period, and usually lasts for 3 to 10 days. "Notably, IRF4 and XBP1 emerge as hub proteins that exhibit multifunctional properties, and diminishing their expression levels could potentially hinder the efficacy of the humoral immune response to the influenza vaccine." (PMID 38400120, 2024). "Transcription factor XBP1 and serine threonine kinase STK11, which are also dependent on ANXA1 for expression after influenza infection, have both been shown to be important in the regulation of autophagy." (PMID 32512864, 2020). "The results showed that both IXA4 and APY29 could activate XBP1 splicing, thereby increasing the expression of SEPT2 in PBMCs collected from influenza patients with cytokine storms." (PMID 37978190, 2023).
injury (4 papers, 2021 to 2023). Damage inflicted on the body as the direct or indirect result of an external force, with or without disruption of structural continuity. "Inhibition of the ER stress-associated IRE-1/XBP-1 (ER processing) signaling pathway suppressed M1 polarization and ameliorated lipopolysaccharide (LPS)-induced lung injury." (PMID 35328434, 2022). "This is consistent with findings from previous literature showing that the inhibition of XBP1 activity reduced NLRP3 inflammasome assembly and caspase-1 processing in a model of hepatic ischemia-reperfusion, thus reducing IRI-triggered liver injury." (PMID 36801911, 2023).
ischemic stroke (4 papers, 2021 to 2024). A stroke disorder caused by obstruction of blood flow to the brain, due to thrombotic (local blood clot formation) or embolic (due to a blood clot or other material traveling from another site) event. "The IRE1/XBP1/OGlcNAc axis emerges as a potential neuroprotective target in ischemic stroke, with Xbp1 deficiency exacerbating outcomes following transient and permanent MCAO." (PMID 38783961, 2024). "MANF and XBP1 are both detected right after ischemic stroke, and their expression is still elevated even 2 weeks after the injury." (PMID 35783104, 2022). "We propose the hypothesis that changes in microRNA levels in the peripheral blood exosomes following ischemic stroke may lead to upregulation of stem cell XBP1 expression in muscle tissue and may thus induce neurogenic ectopic ossification." (PMID 34737845, 2021). "The role of XBP1 and UPR in ischemic stroke has been studied for almost 3 decades." (PMID 35783104, 2022).
liver cancer (4 papers, 2015 to 2024). An epithelial or non-epithelial malignant neoplasm that arises from the liver. "Meanwhile, XBP-1 has been found to be the target of miR199a/214, suggesting that miR199a/214 plays an inhibitory role in liver cancer by inhibiting XBP-1-related pro-survival pathways." (PMID 34659567, 2021). "In liver cancer ATF6 is also responsible for upregulation of XBP1 expression and the activity of both ATF6 and XBP1 increases BiP expression, leading to hepatocarcinogenesis." (PMID 26491226, 2015).
liver inflammation (4 papers, 2017 to 2023). "Another important implication of the present study is that inhibition of XBP1/NLRP3 inflammasome contributes to MSCs-mediated immunomodulation in APAP-induced liver inflammation." (PMID 35842731, 2022). "Our results highlight the importance of the macrophage RIPK3-mediated XBP1–Foxo1–Zc3h15 signalling as a critical regulator of the NOD1 and calcineurin/TRPM7 function in IR-triggered liver inflammation." (PMID 37841640, 2023).
lupus (4 papers, 2014 to 2021). "ALD-DNA alone also caused slight increases in XBP1 and Blimp-1 mRNA expression in lupus B cells." (PMID 25296026, 2014). "Furthermore, ALD-DNA enhanced LPS-triggered plasmablast/plasma cell differentiation program of lupus B cells, as evidenced by increases in CD138+ cell numbers, XBP1 and Blimp-1 mRNA expression as well as IgM production." (PMID 25296026, 2014).
mesothelioma (4 papers, 2009 to 2025). A usually malignant and aggressive neoplasm of the mesothelium which is often associated with exposure to asbestos. "In support of this, our bioinformatic analysis of ADI-PEG20 treated ASS1-negative mesothelioma cells demonstrated significant up-regulation of XBP1 in concert with the pro-inflammatory cytokine response." (PMID 37010783, 2023).
metabolic syndrome (4 papers, 2016 to 2023). A cluster of metabolic risk factors for CARDIOVASCULAR DISEASES and TYPE 2 DIABETES MELLITUS. "IRE1α-XBP1 is the most evolutionarily conserved UPR pathway, and is closely associated with insulin resistance, dyslipidemia, hepatic steatosis and NAFLD inflammation." (PMID 38516345, 2023). "FT@XBP1 supplementation had a significantly attenuated effect on FFC diet-induced weight gain, hepatic fat accumulation, dyslipidemia, inflammatory cytokines, ER stress and fibrosis." (PMID 38516345, 2023).
myocardial infarction (4 papers, 2015 to 2021). Gross necrosis of the myocardium, as a result of interruption of the blood supply to the area, as in coronary thrombosis. "Conversely, the myocardial infarct size and the cardiac impairment of XBP1-overexpressing transgenic mice were reduced after I/R injury, which highlighted the protective effect of XBP1 on cardiomyocytes." (PMID 34917158, 2021). "Myocardial infarction causes the abnormal activation of the UPR and the significantly increased expression of ERS proteins, including GRP78, PERK, ATF6, XBP1, and p-PERK, indicating that myocardial infarction triggered the excessive activation of the ERS pathway." (PMID 34765006, 2021). "Treadmill exercise training can reduce GRP-78, p-PERK, p-eIF2α, ATF-6, XBP1, CHOP, and cleaved-caspase-3 expression to improve the cardiovascular function and reduce myocardial infarction in rats." (PMID 34987702, 2021).
myopia (4 papers, 2015 to 2025). "Based on the gene expression patterns of those pathways, G6pd2 and Rpia in NADPH synthesis and Nme4 and Xbp1 in integrator stress response might be potential candidate genes of oxidative stress on myopia." (PMID 38136985, 2023). "Therefore, the induction of spliced XBP1 in our result supports the activation of the IRE1/XBP1 pathway in the lens epithelium of high myopia-related cataract." (PMID 26351848, 2015). "In the lenses of the age-related and high myopia-related cataract groups, the protein levels of ATF6, p-eIF2α and p-IRE1α and the gene expression levels of spliced XBP1, GRP78, ATF6 and ATF4 were greatly increased." (PMID 26091066, 2015). "Real-time PCR and Western blotting were performed to detect the expression of GRP78, p-eIF2α, spliced XBP1, ATF6, ATF4 and p-IRE1α in the lenses of normal human subjects and patients with age-related, myopia-related or congenital cataracts." (PMID 26091066, 2015).
non-alcoholic steatohepatitis (4 papers, 2015 to 2024). "Likewise, the Xbp1 gene encodes for the X-box binding protein 1, which has a hepatoprotective function against non-alcoholic steatohepatitis." (PMID 39591294, 2024). "Xbp1 is involved in ER stress and is increased in the liver of non-alcoholic steatohepatitis (NASH) patients, increasing fat accumulation and hepatic inflammation." (PMID 36901774, 2023). "Finally, as endoplasmic reticulum stress has been implicated in liver injury such as nonalcoholic steatohepatitis (NASH), we analyzed Xbp1 unprocessed and spliced transcript levels." (PMID 38966569, 2024).
non-small cell lung carcinoma (4 papers, 2021 to 2024). A group of at least three distinct histological types of lung cancer, including non-small cell squamous cell carcinoma, adenocarcinoma, and large cell carcinoma. "However, the clinical significance and pathological role of XBP1 in non-small cell lung cancer (NSCLC) remains unknown." (PMID 34094948, 2021). "IGFBP3 activates the XBP1/IGFBP3/MMP-9 pathways to regulate the invasion and metastasis of non-small cell lung cancer (NSCLC) cells." (PMID 35011220, 2022).
pancreatitis (4 papers, 2011 to 2026). Inflammation of the pancreas. "In fact, the inhibition of the increase of XBP-1 with alcohol feeding results in pancreatitis responses." (PMID 40254129, 2026). "Recently, the importance of X-box binding protein 1 (XBP1) was examined in the context of ethanol-induced sensitivity to pancreatitis." (PMID 22216129, 2011). "Irisin addition up-regulated the expression of pro-survival UPR markers (ATF6 and XBP-1) and reduced UPR pro-apoptotic markers (CHOP) under cer-pancreatitis and induced ER stress (tunicamycin), consequently increasing cells viability." (PMID 38927047, 2024). "Similarly, cer-pancreatitis induction significantly up-regulated the CHOP levels by 7.3-fold (transcript) and by 2-fold (protein), XBP-1 levels by 3.2-fold (transcript) and by 9.7-fold (protein) and Atf6 by 1.6-fold (transcript) compared to the control." (PMID 38927047, 2024). "Pancreatitis induction (cerulein (cer)) resulted in a significant up-regulation of the PPARγ-PGC1α-FNDC5 axis, PL expression and secretion and endoplasmic reticulum (ER) stress unfolded protein response (UPR) signal-transduction markers (CHOP, XBP-1 and ATF6)." (PMID 38927047, 2024).
primary effusion lymphoma (4 papers, 2011 to 2024). A large B-cell lymphoma located in the body cavities, characterized by pleural, peritoneal, and pericardial fluid lymphomatous effusions and that is always associated with human herpes virus-8 (HHV-8). "In the case of gammaherpesviruses, human herpesvirus 8 (HHV8) or Kaposi’s sarcoma associated herpesvirus (KSHV) studies have shown that primary effusion lymphoma (PEL) cells are immunophenotypically similar to pre-plasma cells and have unspliced XBP-1 mRNA." (PMID 30159133, 2018).
Arthritis (3 papers, 2017 to 2024). Inflammation of a joint. "In M1-polarizing conditions, 65–79*SE was predicted to stimulate activation of pro-inflammatory, pro-RA upstream regulators, such as Stat3, Rel, Rela, Jun, Ctnnb1 and Hif1a, among others, and to inhibit anti-arthritis or anti-inflammatory regulators (e.g. Klf2, Xbp1, Foxp3)." (PMID 33510427, 2021). "It was found that absent of IRE1α or XBP1 in chondrocytes spontaneously resulted in OA‐like cartilage destruction and accelerated OA progression in a surgically induced arthritis model, indicating its initial protective role in OA chondrocytes." (PMID 38736291, 2024). "For example, the IRE1α-XBP1 signaling pathway was shown to be a critical element of macrophage responses to TLR ligation, and myeloid-specific knockout of IRE1α ameliorated disease severity in the K/BxN serum-induced arthritis model." (PMID 28923079, 2017).
Autoimmunity (3 papers, 2017 to 2025). The occurrence of an immune reaction against the organism's own cells or tissues. "The reduction of total number of Xbp1pos lymphocytes in the gut closed to lymphoid tissue of the ileum in rats under induced chronic social stress, assuming the role of Xbp1 expression levels as a trigger of inflammation and potential link between stress and autoimmunity." (PMID 28099913, 2017).
B-cell lymphomas (3 papers, 2011 to 2025). "Of note, we found that the 4μ8C/AZD2461 combination was effective also against PEL cells, another B-cell lymphoma known to be strongly dependent on UPR activation, particularly on the IRE1α/XBP1 axis." (PMID 36012375, 2022). "Whether the inhibition of IRE1α/XBP1 axis and PARP could be more cytotoxic than the single treatments against PEL was also evaluated, to assess if this therapeutic strategy could be widened against c-Myc-and gammaherpesvirus-driven B-cell lymphomas." (PMID 36012375, 2022).
breast invasive carcinoma (3 papers, 2021 to 2023). "Notably highest expression of XBP1 was observed in samples from breast invasive carcinoma (SF 1)." (PMID 36997866, 2023).
colon adenocarcinoma (3 papers, 2020 to 2022). "Similarly, in mouse colonic adenocarcinoma CT-26 cells, miR-674-5p expression increased following LPS stimulation and blocking miR-674-5p markedly upregulated sXBP-1 and XBP-1 expression." (PMID 32550011, 2020).
dementia (3 papers, 2019 to 2023). Loss of intellectual abilities interfering with an individual's social and occupational functions. "Several recent studies highlight the potential for the UPRER, specifically XBP1, as a therapeutic target for dementia." (PMID 31570707, 2019). "These assumptions agree with our molecular data showing increased PERK, XBP1, and CHOP expression levels in MCI patients and enhanced ATF6 and BAX in DAT patients, suggesting a pronounced RER stress at the onset of dementia, potentially followed by apoptosis at later stages of the disease." (PMID 37175616, 2023).
diffuse large B-cell lymphoma (3 papers, 2019 to 2022). "LINC00963/miR-320a axis was found to regulate endoplasmic reticulum stress and autophagy in vitro of diffuse large B-cell lymphoma, this regulatory role of which was closely associated with XBP1." (PMID 34112145, 2021). "Nuclear XBP1 expression in diffuse large B-cell lymphoma was correlated with poorer response to therapy and shorter overall survival in contrast to tumors with non-expressing XBP1." (PMID 35626128, 2022). "In summary, LINC00963/miR-320a/XBP1 could be potential molecular markers and targets for the diagnosis and treatment of diffuse large B-cell lymphoma." (PMID 34112145, 2021).
dwarfism (3 papers, 2015 to 2022). "Together, these data suggest a more prominent contribution of the PERK-p-eIF2 signaling pathway than that of Xbp1S, which is consistent with another MCDS mouse model study that found inactivation of Xbp1 in HCs did not alter the severity of dwarfism." (PMID 30024379, 2018).
esophageal squamous cell carcinoma (3 papers, 2015 to 2021). Esophageal squamous cell carcinoma (ESCC) is a type of esophageal carcinoma (EC) that can affect any part of the esophagus, but is usually located in the upper or middle third. "Also, in esophageal squamous cell carcinoma (ESCC), XBP1 is overexpressed in both cell lines as well as in clinical tumor samples, correlating with tumor stage, lymph node metastasis, and poor patient outcome." (PMID 33746610, 2021).
gastric cancer (3 papers, 2018 to 2025). A primary or metastatic malignant neoplasm involving the stomach. "Finally, five proteins, including NDRG1_pT346, SYK, P90RSK, TIGAR, and XBP1, were related to the risk prognosis of gastric cancer and were selected for model construction." (PMID 36979962, 2023). "However, the role of XBP1 in gastric cancer remains unknown and needs to be further explored." (PMID 36979962, 2023). "Moreover, dhCer influences ER stress pathways in gastric carcinoma cells treated with DEGS inhibitor by activating the translation inhibitor eIF2α and splicing the pro-survival transcription factor Xbp1, contributing to a cellular survival response." (PMID 40075756, 2025). "Although XBP1 has not been related to gastric cancer so far, it is the only overlapping transcription factor (TF) in the three top-100 DGR lists across Chinese, Korean and American." (PMID 29745833, 2018).
hypothyroidism (3 papers, 2018 to 2021). Abnormally low levels of thyroid hormone. "This treatment also prevented hypothyroidism-induced overexpression of IRE1α, XBP1, and caspase 12 (40, 41, and 200% respectively compared with the euthyroid group)." (PMID 34295248, 2021). "The expression of XBP1 was not modified during hypothyroidism, indicating that ribonuclease activity of IRE1α was not increased as a response for this condition." (PMID 29743975, 2018).
insulinoma (3 papers, 2012 to 2021). "As in the case of 4μ8C, the MKC-3946 mutant abolished proinsulin-induced XBP1 mRNA splicing in insulinoma cell line." (PMID 33562589, 2021). "Similar to insulinoma cells, primary rat islets treated with thapsigargin readily increased expression of ER stress markers, namely XBP-1(s), CHOP, and PUMA." (PMID 28212395, 2017). "In primary islets and insulinoma cells, ER stress activates a strong stress response program as indicated by the upregulation of XBP-1(s), BiP, CHOP, GADD34 and other factors." (PMID 28212395, 2017). "ER redox was also unaltered in insulinoma cells exposed to chronic palmitate or homocysteine treatment, both of which induced ER stress as detected by spliced XBP-1 mRNA levels." (PMID 23144914, 2012). "The levels of XBP-1(u), XBP-1(s), PUMA, and ATF4 mRNA were similar or slightly elevated in islets relative to insulinoma cells." (PMID 28212395, 2017). "By contrast, 4μ8C inhibited the XBP1 mRNA splicing in response to ER stress triggered by mutant proinsulin (C96Y) production in insulinoma cell line; however, the inhibition affected neither ERAD nor ER stress-induced apoptosis." (PMID 33562589, 2021).
nasopharyngeal carcinoma (3 papers, 2019 to 2025). A carcinoma arising from the nasopharyngeal epithelium. "XBP1 is frequently detected in nasopharyngeal carcinoma (NPC) cancers." (PMID 31151143, 2019).